KLHDC7B (kelch domain containing 7B)
Synonyms: MGC16635
Tractability: Antibody: the Human Protein Atlas places it where antibodies can reach.
Gene: Protein-coding gene on chromosome 22 (50,545,899 to 50,551,023, forward strand). Ensembl gene ENSG00000130487.
Subcellular location (Human Protein Atlas): Plasma membrane
Genetic constraint (gnomAD): Loss-of-function variants: 3 observed, 1.42 expected, observed/expected ratio (o/e) 2.11. That is too few expected variants to judge how well the gene tolerates losing a copy. Missense variants: 949 observed, 764.27 expected, observed/expected ratio (o/e) 1.24, 90% interval 1.18 to 1.31. Synonymous variants: 444 observed, 338.27 expected, observed/expected ratio (o/e) 1.31, 90% interval 1.21 to 1.42.
Homologues: Orthologues: mouse Klhdc7b (52% identical), rat Klhdc7b (50% identical), chimpanzee KLHDC7B (47% identical), dog KLHDC7B (44% identical). Paralogues in human: KBTBD11 (17% identical), KLHDC7A (17% identical), KLHL42 (9% identical), KLHL21 (9% identical), KLHL29 (9% identical), KLHL1 (9% identical), KLHL4 (9% identical), KLHL31 (8% identical), KLHL22 (8% identical), KLHL33 (8% identical), KLHL26 (8% identical), KLHL5 (8% identical), and 42 more.
Diseases named in the same sentence as KLHDC7B in open-access papers:
KLHDC7B is named in the same sentence as 24 diseases in open-access papers, as found by Europe PMC text mining. Sharing a sentence is not in itself a finding about the gene and the disease. The quoted sentences say what the papers report.
breast carcinoma (10 papers, 2012 to 2024). "As far as we know, this is the first report of the association of KLHDC7B or LncKLHDC7B expression with poor prognosis in breast cancer." (PMID 30648789, 2019). "In conclusion, a lncRNA, STAR1, was upregulated in breast cancer and its expression showed a significant association with KLHDC7B; dysregulation accompanied the alteration of STAR1 expression." (PMID 30150751, 2018). "In this study, we identified a long non-coding RNA, ST8SIA6-AS1 (STAR1), whose expression was significantly associated with KLHDC7B in breast cancer (R2 = 0.3466, P < 0.01)." (PMID 30150751, 2018). "As STAR1 has a significant association of expression with KLHDC7B in breast cancer, a cell proliferation assay was carried out to compare their effect on cell growth." (PMID 30150751, 2018). "In the same way, in breast cancer samples, the promoter of the KLHDC7B gene was hypermethylated and associated with its overexpression in comparison with normal mammary tissue." (PMID 22880087, 2012). "Additionally, in silico analysis confirmed for the first time that the low expression of KLHDC7B and LncKLHDC7B is associated with poor prognosis in patients with breast cancer." (PMID 30648789, 2019). "For example, it is proven that KLHDC7B regulates interferon signaling pathway, which is critical for breast cancer tumorigenesis." (PMID 38783355, 2024). "For example, MORF4L2, PKG1, VPS28, and KLHDC7B predict the survival time of patients, indicating that cancer domains also facilitate the identification of bio-markers for breast cancer." (PMID 38783355, 2024). "KLHDC7B, CASP14, and PRSS1 are putatively oncogenic gene that has been demonstrated in breast cancer and pancreatic cancer, and the role of KLHDC7B was correlated with extracellular communication, cell morphology, gene expression, and actin binding." (PMID 33987102, 2021). "KLHDC7B was shown to influence the breast cancer proliferation, BRD4 was reported to influence the immune cell infiltration in breast cancer and promote the cMYC downstream genes’ transcription." (PMID 32500914, 2020). "Several lines of evidence indicated the importance of the LncKLHDC7B/KLHDC7B pair of transcripts, including that LncKLHDC7B expression is specific for the IM subtype (or, based on our analyses, on breast cancer in a generalized way)." (PMID 30648789, 2019). "To explore further the altered expression of LncKLHDC7B and KLHDC7B and their clinical implication in breast cancer, we evaluated the correlation between their expression and survival probability in a public database." (PMID 30648789, 2019). "Our results suggest a significant association of expression between KLHDC7B and STAR1 in breast cancer." (PMID 30150751, 2018). "In this study, genes affected by KLHDC7B were identified in the MCF-7 breast cancer cell line after inducing up- and downregulation of the gene." (PMID 30150751, 2018). "Taken together, KLHDC7B and STAR1 are both overexpressed in breast cancer and significantly associated with gene modulation activity in the interferon signaling pathway during breast tumorigenesis." (PMID 30150751, 2018). "Expression of STAR1 was upregulated in breast cancer cell lines and also in breast cancer tissue compared to its nearby normal tissue (N = 30, P-value < 0.05), similar to KLHDC7B (N = 28, P-value < 0.05)." (PMID 30150751, 2018). "An association of statistical significance was found between KLHDC7B and STAR1 expression in breast cancer tissues (R = 0.5887, P-value < 0.01)." (PMID 30150751, 2018). "KLHDC7B was identified in our previous study to be hypermethylated at the promoter and upregulated in breast cancer patients." (PMID 30150751, 2018). "In our previous study, the Kelch domain-containing 7B (KLHDC7B) was revealed to be hypermethylated at the promoter but upregulated in breast cancer." (PMID 30150751, 2018).
breast carcinoma (continued). "It appears uncommon for two genes, KLHDC7B and STAR1, to show opposite effects on the cell proliferation or apoptosis while their expression is significantly associated in breast cancer." (PMID 30150751, 2018). "First, the gene was downregulated in the MCF-7 using a siRNA, which is a breast cancer cell line and expresses KLHDC7B at an elevated level." (PMID 30150751, 2018). "Both CHKB and KLHDC7B are located on chromosome 22q13.33, where KLHDC7B is involved in breast cancer and lymph node metastasis in cervical cancer and CHKB encodes choline kinase (ChoK) beta." (PMID 25106096, 2014). "The promoter region of KLHDC7B is a rarely hypermethylated gene in breast cancer cell lines." (PMID 34799565, 2021). "Down‐regulation of KLHDC7B was associated with lower disease‐free survival and LncKLHDC7B was closely associated with poor clinical outcome in triple‐negative tumors and breast cancer in general." (PMID 30648789, 2019). "In the current study, we aimed to clarify the roles of KLHDC7B and STAR1 lncRNA in the molecular events during the proliferation of breast cancer cells." (PMID 30150751, 2018). "Both KLHDC7B and STAR1 were upregulated in breast cancer tissue." (PMID 30150751, 2018).
hearing loss (4 papers, 2020 to 2025). "In both models, loss of Klhdc7b in mice resulted in an early onset and fast progressing hearing loss, whereas data from human GWAS has suggested that variation in KLHDC7B is associated with increased risk of ARHL, a much later onset phenotype." (PMID 41407909, 2025). "While the biological effect of the missense is difficult to interpret, the association of putative LOFs with increased risk for hearing loss suggests that loss of KLHDC7B function is deleterious for hearing function." (PMID 35661827, 2022). "The same study also utilized whole exome sequencing data to perform a rare variant analysis (minor allele frequency < 0.01), identifying heterozygous predicted loss-of-function variants in KLHDC7B associated with increased risk of hearing loss, with an odds ratio of 2.145." (PMID 41407909, 2025). "In addition, we observed a common (MAF = 0.04) missense variant (Val504Met) within the last Kelch domain of KLHDC7B associated with increased risk for hearing loss (OR = 1.14, P = 4 × 10−26)." (PMID 35661827, 2022). "The most significant rare coding association in our analysis was the aggregate of 68 pLOF variants (43 frameshift, 23 stop-gain and 2 stop-loss,) in KLHDC7B (Kelch-like domain containing 7B), with an approximately two-fold increase in risk for hearing loss (OR = 2.14, P = 5 × 10−30)." (PMID 35661827, 2022).
cervical cancer (3 papers, 2014 to 2025). A primary or metastatic malignant neoplasm involving the cervix. "The analysis showed that OAS2, KLHDC7B, STAT1, TYMP, PSME2 and GBP5 were significantly upregulated in cervical cancer cells compared with normal epithelial cells." (PMID 40259929, 2025).
bladder cancer (2 papers, 2023 to 2025). "It was found that KLHDC7B, the mRNA downregulated the most by JorA, was highly expressed in bladder cancer and associated with a poor prognosis in patients with bladder cancer." (PMID 37587470, 2023). "RNA-seq of urinary exosomes from 12 bladder cancer patients and 6 healthy controls identified KLHDC7B as upregulated in bladder cancer patients." (PMID 40075875, 2025). "KLHDC7B has been demonstrated to be a marker in urine exosomes that can be used to detect the tumor progression of bladder cancer, and its mRNA imbalance is related to tumor stage and grade as well as hematuria degree." (PMID 37587470, 2023).
cervical squamous cell carcinoma (2 papers, 2019 to 2025). A squamous cell carcinoma arising from the cervical epithelium. "On the other hand, KLHDC7B has been implicated in the development and progression of cervical squamous cell carcinoma (CSCC) through different mechanisms, including the alternative splicing (AS) site in the KLHDC7B gene, which was present in 67.5% of CSCC samples." (PMID 40508156, 2025). "Further evidence of the potential role of the LncKLHDC7B–KLHDC7B correlated expression in cancer comes from the recent description of a novel 5′ alternative splicing site in the KLHDC7B gene in cervical squamous cell carcinoma." (PMID 30648789, 2019).
Hematuria (2 papers, 2021 to 2023). The presence of blood in the urine. "Remarkably, we also found the expression of exosomal GAS5 was significantly negatively associated with the tumor grade and degrees of hematuria (all P < 0.05), whereas, the exosomal KLHDC7B, CASP14, PRSS1, and MIR205HG showed positive correlation with tumor grade and hematuria degrees." (PMID 33987102, 2021).
laryngeal carcinoma (2 papers, 2022 to 2024). Carcinoma that arises from the laryngeal epithelium. "For example, it has been regularly reported that laryngeal cancer tissues differentially express certain genes, including EMP1, HOXB9, DPY19L2P1, MMP1, and KLHDC7B, representing independent prognosis predictor genes of laryngeal cancer." (PMID 39452555, 2024).
age-related hearing loss (1 paper, 2025). "Our results here demonstrate that Klhdc7b, the ortholog of a novel gene strongly associated with hearing loss in several recent human GWAS focused on age-related hearing loss, is necessary for the maintenance of hearing in mice." (PMID 41407909, 2025). "Using two independent knockout mouse models, the authors show that loss of Klhdc7b, a candidate for susceptibility to age-related hearing loss in humans, results in an early and progressive hearing loss, confirming Klhdc7b’s role in the maintenance of hearing." (PMID 41407909, 2025).
bladder urothelial carcinoma (1 paper, 2025). "In addition, KLHDC7B has been found to promote the proliferation and migration of bladder urothelial carcinoma cells." (PMID 40259929, 2025).
Chlamydia (1 paper, 2012). "KLHDC7B was upregulated during vulvar intraepithelial neoplasia due to human papillomaviruses and in dendritic cells infected with Chlamydia pneumonia." (PMID 22590687, 2012).
colon cancer (1 paper, 2021). "The expression level of KLHDC7B mRNA was significantly increased in HeLa cells after 12 h of incubation with SubAB In addition, we also found that SubAB increased KLHDC7B mRNA levels in the human colon cancer HCT116 cell line." (PMID 34799565, 2021).
multiple sclerosis (1 paper, 2023). A progressive autoimmune disorder affecting the central nervous system resulting in demyelination. "ENSG00000273272 has not been studied yet and no function is associated with this gene, ODF3B has been associated with SSc and multiple sclerosis, and KLHDC7B has been linked to the IFN signaling pathway." (PMID 37475860, 2023).
tumor (10 papers, 2015 to 2025). "It has also been demonstrated that the knockdown of KLHDC7B suppressed the tumor-promoting effects, which included increased proliferation, migration, invasion, and decreased apoptosis in CC cells." (PMID 40508156, 2025). "Kelch domain containing 7B (KLHDC7B) is a tumor marker with epigenetic differences in breast and laryngeal cancers." (PMID 34799565, 2021). "We first corroborated the positive correlation in the expression of LncKLHDC7B and KLHDC7B in independent tumor datasets and in cell lines." (PMID 30648789, 2019). "We analyzed the role of ICDRs in tumor immune microenvironment by using the previous data of single cell transcriptome, and we analyzed the distribution of several key genes (PSME2, TYMP, KLHDC7B, GBP5, EPSTI1, STAT1 and OAS2) in different cell types." (PMID 40259929, 2025). "On the other hand, in domain 4, we observed upregulation of KRT8, AQP3, KLHDC7B and CDH1, which tend to exhibit stronger tumor progression and metastasis, and high expression of genes NUPR1 and DBI associated with chemotherapy resistance." (PMID 36250636, 2022). "Interestingly, this dual role of KLHDC7B and GAS5 during tumor progression has also been found in other studies." (PMID 33987102, 2021).
cancer (6 papers, 2018 to 2025). A tumor composed of atypical neoplastic, often pleomorphic cells that invade other tissues. "KLHDC7B plays a role in cytoskeletal organization, protein degradation, and gene expression, and has shown clinical utility as a prognostic marker in pan-cancer studies." (PMID 40429863, 2025). "In contrast to other proteins in that class, the detailed protein structure and function of KLHDC7B in normal cells, as well as cancer cells, has yet to be determined." (PMID 30150751, 2018). "As a result, expression of six genes was in the same direction of the KLHDC7B-downregulation, supporting the theory that KLHDC7B and STAR1 function through opposing mechanisms on the cancer cell activity through interferon signaling." (PMID 30150751, 2018). "In order to examine the effect of KLHDC7B and STAR1 on the proliferation of cancer cells, the proliferation of MDA-MB-231 was analyzed after inducing each gene deregulation." (PMID 30150751, 2018). "All these genes may stimulate metastasis in various cancers, and notably, their expression was opposite or not significantly changed in the KLHDC7B-downregulated cells." (PMID 30150751, 2018).
KLHDC7B also shares sentences with these, for which no sentence is quoted: age (1 paper); autism spectrum disorder (1); bladder tumors (1); breast tumors (1); COVID-19 (1); deafness (1); depression (1); lymph node metastasis (1); pancreatic cancer (1); vulvar intraepithelial neoplasia (1).